GUCY2C (guanylate cyclase 2C)
Diseases named in the same sentence as GUCY2C in open-access papers (continued):
Sharing a sentence is not in itself a finding about the gene and the disease.
Crohn disease (3 papers, 2013 to 2023). A gastrointestinal disorder characterized by chronic inflammation involving all layers of the intestinal wall, noncaseating granulomas affecting the intestinal wall and regional lymph nodes, and transmural fibrosis. "In addition to disorders associated with deregulated luminal hydration, a consequence of Gucy2c mutation is susceptibility to IBDs such as Crohn’s disease." (PMID 24244444, 2013).
esophageal cancer (3 papers, 2017 to 2023). A primary or metastatic malignant neoplasm involving the esophagus. "Beyond CRC, GUCY2C is ectopically expressed in approximately 60% of pancreatic, gastric, and esophageal cancers." (PMID 31010434, 2019). "In addition, GUCY2C is expressed in approximately 60% of pancreatic, gastric, and esophageal cancers, suggesting that GUCY2C could be targeted in those diseases as well." (PMID 28914772, 2017).
Diarrhea (2 papers, 2022 to 2025). Abnormally increased frequency (usually defined as three or more) loose or watery bowel movements a day. "CEAS/CNSU caused by SLCO2A1 defects, as well as congenital/familial diarrhea associated with SLC26A1, SLC9A3, and GUCY2C mutations, were the most prevalent monogenic disorders in patients with LO-mIBD, significantly more common than in those with IO-mIBD (p < 0.001)." (PMID 40474095, 2025). "The classical, i.e. non-syndromic, congenital sodium diarrhea is caused by either an autosomal recessive loss-of function-mutation in the Slc9a3 gene or by a dominant gain-of-function mutation in GUCY2C, the gene encoding intestinal receptor guanylate cyclase C (GCC)." (PMID 35665228, 2022).
hepatoma (2 papers, 2012 to 2022). "Moreover, elevated basal systemic genotoxicity reflecting barrier corruption potentiated induction of hepatoma by the chemical carcinogen azoxymethane (AOM) in Gucy2c−/−, but not in Gucy2c+/+, mice." (PMID 22384056, 2012).
intestinal obstruction (2 papers, 2013 to 2016). Blockage of the normal flow of the intestinal contents within the bowel. "This pivotal role of GCC signaling in intestinal fluid balance is most poignantly illustrated by gain- and loss-of-function mutations in GUCY2C (encoding GCC), which have been shown to cause secretory diarrhea and intestinal obstruction, respectively." (PMID 27246004, 2016).
Parkinson's (2 papers, 2024 to 2025). "Together, these findings offer compelling evidence that cyclic nucleotide-mediated signaling, whether through PDE inhibition or GUCY2C activation, holds promise as a novel therapeutic avenue for addressing striatal dopamine deficiency in neurodegenerative disorders such as Parkinson’s disease." (PMID 39456033, 2024). "To assess the efficacy of PDE inhibition and Gucy2C activation treatments, we employed the apomorphine rotations test, a valuable tool for the in vivo treatment efficacy in Parkinson's disease." (PMID 39456033, 2024). "Interestingly, GUCY2C is enriched in midbrain dopaminergic neurons, making it a promising target for promoting cyclic nucleotide signaling in Parkinson’s disease." (PMID 39456033, 2024). "Furthermore, both PDE2A inhibition and GUCY2C activation ameliorated motor impairments in a Parkinson’s disease mouse model with partial 6-OHDA lesions." (PMID 39456033, 2024). "In conclusion, both PDE inhibition via the PDE2A inhibitor PF05180999 and Gucy2C activation via guanylin effectively alleviate motor complications induced by dopamine deafferentation in the 6-OHDA Parkinson's disease mouse model, to a similar extent as the gold standard treatment, L-DOPA." (PMID 39456033, 2024). "Furthermore, both PDE inhibition and GUCY2C activation resulted in improved motor behavior in the 6-OHDA Parkinson’s disease mouse model, highlighting the potential therapeutic benefits of these approaches." (PMID 39456033, 2024). "Our findings suggest that enhancing cyclic nucleotide signalling—whether via PDE inhibition or GUCY2C activation—holds considerable promise for treating Parkinson’s disease by boosting endogenous dopamine production through tyrosine hydroxylase Ser40 phosphorylation." (PMID 39456033, 2024). "Specifically, we explore the effects of phosphodiesterase (PDE) inhibition and guanylate cyclase-C (GUCY2C) activation on tyrosine hydroxylase Ser40 phosphorylation and their impact on motor behavior in a 6-hydroxydopamine (6-OHDA) Parkinson's disease model." (PMID 39456033, 2024).
adenoma (1 paper, 2025). A neoplasm arising from the epithelium. "These molecular alterations in intestinal epithelial stem cells are known to develop into metaplasia marked by higher expression of Guanylyl cyclase C (GUCY2C), which is a premalignant condition that increases the risk of progression to dysplasia, adenoma, and adenocarcinoma." (PMID 40710193, 2025).
diarrhea syndrome (1 paper, 2021). "A novel preclinical mouse model harboring an activating mutation in Gucy2c demonstrates features seen in patients with familial GUCY2C diarrhea syndrome." (PMID 34546338, 2021).
endometriosis (1 paper, 2023). The growth of functional endometrial tissue in anatomic sites outside the uterine body. "Moreover, beyond pain associated with chronic constipation syndromes, mechanisms here likely mediate the analgesic effects of GUCY2C agonists on VP associated with chronic bladder dysfunction and endometriosis." (PMID 36548082, 2023). "Oral linaclotide could modulate these dual-innervating afferents by stimulating GUCY2C in neuropod cells in the small intestine to reduce VP signaling from colorectal distention, as well as from bladder irritation and endometriosis." (PMID 36548082, 2023).
intestinal cancer (1 paper, 2014). "Additionally, endogenously expressed GUCY2C internalized to lysosomes in STC1 murine intestinal cancer cells." (PMID 25294806, 2014).
radiation-induced gastrointestinal syndrome (1 paper, 2017). "Moreover, the present study reveals that silencing the GUCY2C axis exacerbates the radiation-induced gastrointestinal syndrome (RIGS), the pathophysiology of which has been largely attributed to damage and death of ISCs." (PMID 29262534, 2017).
tumor (38 papers, 2010 to 2025). "As a result, tumor progression through the APC pathway involves loss of the hormone GUCA2A that suppresses the tumor-suppressing receptor GUCY2C." (PMID 35907803, 2022). "A recent study suggests that GUCY2C can suppress tumor progress in the intestine, and the loss of the GUCY2C signaling cascade increases CRC susceptibility." (PMID 31467713, 2019). "An alternative view recognizes that endogenous GUCY2C ligands are suppressed early in transformation (again, by a mechanism yet to be defined), suggesting that a paracrine field of GUCY2C silencing is responsible for cGMP loss and tumor susceptibility." (PMID 30131940, 2018). "Beyond secretion, GUCY2C is a tumor suppressor universally silenced by loss of expression of its paracrine hormone during carcinogenesis." (PMID 28895923, 2017). "Interestingly, deletion of CDX2, the intestinal transcription factor responsible for GUCY2C expression, similarly potentiates tumor burden, chromosomal aberrations, and APC loss of heterozygosity." (PMID 30131940, 2018). "Nevertheless, GUCY2C gene expression by microarray was associated with increasing metastatic potential in a study of primary ccRCC tumors, suggesting that further study of this gene in a larger dataset of metastatic tumor tissue is warranted." (PMID 27574806, 2016). "One significant advancement in CAR T cell therapy for GI cancers is the identification of tumor-specific antigens, such as guanylyl cyclase C (GUCY2C) and claudin 18.2 (CLDN18.2)." (PMID 40297102, 2025). "Similar findings were reported for the gene encoding GUCY2C, which is elevated in CRC but serves as a tumor suppressor." (PMID 33680927, 2020). "These promising preclinical reports support approaching tumor prevention through reconstitution of the silenced GUCY2C-cGMP signaling axis." (PMID 30131940, 2018). "Beyond intestinal secretion, the guanylin-GUCY2C paracrine axis comprises a tumor suppressing circuit whose dysregulation universally characterizes colorectal carcinogenesis across species." (PMID 28895923, 2017). "GUCY2C recently emerged as an intestinal tumor suppressor coordinating AKT1-dependent crypt-villus homeostasis." (PMID 22384056, 2012). "This inverse correlation may be attributed to the involvement of GUCY2C as a tumor suppressor in CRC pathophysiology, particularly in developing countries." (PMID 37927469, 2023). "In the context of the role of GUCY2C as a tissue-specific tumor suppressing receptor, the present observations expand that function beyond transformation in the colorectum, to neoplasia in lymph nodes, liver, and lung through maintenance of epithelial barrier integrity." (PMID 22384056, 2012). "We also detected the expression of CDH17 and GUCY2C in 13 tumor cell lines by RT-PCR, and found that CDH17 and GUCY2C have a pronounced co-expression in various tumor cells." (PMID 40721409, 2025). "ST stimulation of GUCY2C arrests cell proliferation, suggesting an intriguing hypothesis that chronic ETEC colonization confers tumor resistance." (PMID 30131940, 2018). "This does not negate the potential for on-target, off-tumor toxicity in the clinic due to differential expression of GUCY2C between mice and humans." (PMID 28914772, 2017).
cancer (19 papers, 2010 to 2025). A tumor composed of atypical neoplastic, often pleomorphic cells that invade other tissues. "In the spectrum of 33 human cancer types, GUCY2C demonstrates a similar expression pattern to CDH17." (PMID 40721409, 2025). "GUCY2C, a surface membrane glycoprotein expressed on gastrointestinal tumor cells, represents an attractive target for T-cell immunotherapy against cancer." (PMID 37591971, 2023). "Beyond secretion, GUCY2C regulates intestinal epithelial homeostasis, including key component processes canonically disrupted in cancer." (PMID 28895923, 2017). "Indeed, ~ 25% of all cancer-related deaths in the U.S result from malignancies that may express GUCY2C and which may be treated with GUCY2C-targeted therapies." (PMID 31010434, 2019). "In addition, five genes involved in the 47-mRNA metastasis-related model, including FABP4, GUCY2C, MEIS2, POU1F1, and SLC25A11 have been reported to be related to the metastasis of other human cancers." (PMID 33159021, 2020).
infection (5 papers, 2013 to 2025). The state of being infected such as from the introduction of a foreign agent such as serum, vaccine, antigenic substance or organism. "Interestingly, the expression of CYBB, JAK3, and GUCY2C was also turned off after vPdR-H30K-5U infection." (PMID 40006915, 2025).
gastrointestinal disease (1 paper, 2019). A disease that occurs in the gastrointestinal system, excluding the hepatobiliary system. "Guanylate cyclase-C (GC-C) is a multifunctional receptor encoded by the GUCY2C gene, representing an attractive target for therapy in several gastrointestinal diseases in humans." (PMID 31611814, 2019).
GUCY2C also shares sentences with these, for which no sentence is quoted: irritable bowel syndrome (14 papers); colon carcinoma (11); pancreatic cancer (6); adenocarcinoma (3); Constipation (3); intestinal disorder (3); lymph node metastases (3); Chronic colitis (2); Chronic constipation (2); cystic fibrosis (2); esophagitis (2); gastric cancer (2); gastrointestinal disorders (2); gastrointestinal tumor (2); acute myeloid leukaemia (1); attention deficit-hyperactivity disorder (1); bacterial infection (1); Chronic diarrhea (1); chronic pancreatitis (1); colorectal adenoma (1); duodenitis (1); dysplasia (1); eating disorder (1); esophageal adenocarcinoma (1); esophageal SCCs (1); esophageal tumors (1); inflammation (1); Insulin resistance (1); metastatic cancers (1); ovarian carcinoma (1).
A further 8 diseases each share a sentence with GUCY2C in 1 paper.